NEAT1 (nuclear paraspeckle assembly transcript 1)
Diseases named in the same sentence as NEAT1 in open-access papers (continued):
Sharing a sentence is not in itself a finding about the gene and the disease.
Sepsis (continued). "In this study, miR-370-3p was confirmed to be the target of NEAT1, and the level of miR-370-3p was apparently downregulated in sepsis tissues and LPS-induced RAW 264.7 and HL-1 cells." (PMID 32414769, 2020). "Recent evidence also has confirmed that patients with sepsis tend to have high levels of NEAT1, increased disease severity, and poor prognosis." (PMID 32089649, 2020). "Other examples were seen in the blood of patients with sepsis or acute ischemic stroke, where the expression of NEAT1 was increased and positively correlated with IL-8." (PMID 33193674, 2020). "Nuclear enriched abundant transcript 1 (NEAT1) was detected as significantly upregulated in the serum of patients with sepsis-induced as well as in patients with ischemia-induced AKI." (PMID 31277300, 2019). "In our study, NEAT1 was significantly upregulated in the PBMCs of patients with sepsis, consistent with the excessive inflammatory response during sepsis observed in clinical studies." (PMID 29463949, 2017). "In conclusion, upregulated NEAT1 expression in patients with sepsis was discovered for the first time in our study, indicating an association between NEAT1 and immune dysfunction in patients with sepsis." (PMID 29463949, 2017). "Based on an extensive literature review, the lncRNA molecule NEAT1 was identified as a candidate biomarker for sepsis." (PMID 29463949, 2017). "Further ROC curve analysis revealed that NEAT1 has clinical value for sepsis diagnosis, which is more useful for SIRS diagnosis." (PMID 29463949, 2017). "NEAT1 with an area under the curve (AUC) of 0.851 (95% CI: 0.812–0.935) indicated sensitivity (67.85%) and specificity (87.27%) for the diagnosis for sepsis, the positive predictive value (PPV) was 83.3%, and the negative predictive value (NPV) was 71.6%." (PMID 29463949, 2017). "These limitations will guide future in-depth studies of the use of NEAT1 as a molecular marker for sepsis diagnosis." (PMID 29463949, 2017). "Compared with healthy controls, NEAT1 expression of PBMCs in sepsis and SIRS groups were significantly increased (3.76 ± 0.71- and 1.64 ± 0.43-fold, resp)." (PMID 29463949, 2017). "NEAT1 is a potential molecular marker for sepsis diagnosis, offering a new option for early diagnosis." (PMID 29463949, 2017). "Similarly, in sepsis, a ceRNA regulatory pattern was observed where lncRNA NEAT1 sponges miR-370-3p." (PMID 40696462, 2025). "Additionally, the RNA levels of NEAT1 are often positively correlated with the severity of the infection, such as with sepsis." (PMID 40362651, 2025). "The expression of NEAT1 is significantly high in a subset of PBMCs driven by sepsis." (PMID 40362651, 2025). "There is a significant positive correlation between NEAT1 and the severity of sepsis, indicating that NEAT1 may serve as a potential biomarker for sepsis." (PMID 40362651, 2025). "Based on the ceRNA hypothesis, one downregulated miRNA and one upregulated lncRNA previously reported in sepsis were selected, resulting in the proposal of the following ceRNA network: NEAT1-Homo sapiens (hsa)-miR-495-3p-ELF1." (PMID 40821971, 2025). "Furthermore, lncRNA NEAT1 was found to be elevated in the serum of patients with sepsis-induced AKI compared to controls, showing a positive correlation with the severity of AKI." (PMID 40657645, 2025). "NEAT1 expression is significantly upregulated in sepsis patient samples." (PMID 40362651, 2025). "NEAT1 expression is significantly upregulated in the PBMCs of sepsis patients." (PMID 40362651, 2025). "In addition, a recent study has demonstrated that NEAT1 promotes M2 polarization via miR-125a-5p/TRAF6/TAK1 axis, thus modulating LPS-induced inflammation, supporting the role of NEAT1 in macrophage polarization during sepsis-inflammatory responses." (PMID 38395749, 2024). "The levels of NEAT1 are increased by more than two-fold in the sera of sepsis patients." (PMID 38473915, 2024).
Sepsis (continued). "Our findings might unravel a specific ATF3/ILF3/NEAT1 mechanism and provide promising therapeutic targets and profound implications for targeted therapy of sepsis." (PMID 38395749, 2024). "The ATF3/ILF3/NEAT1 axis ameliorated sepsis-induced ALI via modulating M2 polarization." (PMID 38395749, 2024). "NEAT1 exacerbates sepsis-induced ARDS via miR-27a/PTEN axis." (PMID 38395749, 2024). "In addition, some studies have confirmed that NEAT1 alleviates sepsis-induced myocardial injury by regulating TLR2/NF-κB signaling pathway." (PMID 36817458, 2023). "During sepsis, increased levels of the long non-coding RNA nuclear enriched abundant transcript-1 (NEAT1) could be detected in blood, which correlated with the degree of sepsis-induced AKI." (PMID 37542608, 2023). "It has been confirmed that interfering with the expression of lncRNA NEAT1 and lncRNA PVT1 could reduce apoptosis to facilitate the kidney cell injury caused by sepsis." (PMID 35464083, 2022). "To explore whether exosome derived NEAT1 functions in sepsis-induced ferroptosis, we investigated potential downstream signaling molecule of NEAT1 in bEnd.3 cells." (PMID 35038133, 2022). "The present study aimed to figure out whether exosomal lncRNA NEAT1 affects sepsis-induced ferroptosis through NEAT1/miR-9-5p/TFRC and GOT1 axis." (PMID 35038133, 2022). "Furthermore, NEAT1 has been shown to be positively correlated with the severity of AKI, the increased disease risk, and the unfavorable prognosis in sepsis patients." (PMID 35464083, 2022). "We suspected that NEAT1 might be a valuable biomarker for the identification of sepsis-induced ferroptosis and SAE." (PMID 35038133, 2022). "In rats, NEAT1 knockdown could significantly improve the sepsis-induced myocardial injury preventing cardiac insufficiency and consensually increasing the ejection fraction (p < 0.05)." (PMID 35741168, 2022). "In conclusion, these findings suggest that sepsis induced high expression of serous exosome-derived NEAT1, and it might exacerbate SAE by promoting ferroptosis through regulating miR-9-5p/TFRC and GOT1 axis." (PMID 35038133, 2022). "In addition, the expression of lncRNA NEAT1 was upregulated in the sera of patients with sepsis and in the LPS-induced human renal tubular epithelial cell line HK-2." (PMID 36429069, 2022). "NEAT1 was reportedly up-regulated in peripheral blood mononuclear cells (PBMCs) of patients with sepsis, with high sensitivity (67.85%) and specificity (87.27%) for sepsis diagnosis; however, no statistically significant relevance was observed between the sepsis survivors and non-survivors." (PMID 34055659, 2021). "Long noncoding RNA NEAT1 modulates sepsis-related AKI by regulating miR-204/NF-κB signaling." (PMID 34250012, 2021). "Another in vitro study demonstrated that NEAT1 was observed to regulate miR-495-3p/signal transducers and activators of transcription axis and miR-211/phosphoinositide-3-kinase/protein kinase B axis in inflammatory process of sepsis." (PMID 34630395, 2021). "This suggested that NEAT1 could be used as a potential and effective marker for rapid diagnosis of sepsis." (PMID 34630395, 2021). "Likewise, CRNDE and NEAT1 promoted the progression of sepsis-induced injury by regulating the NF-κB signaling." (PMID 34630395, 2021). "Downregulation of NEAT1 reduced expression of inflammatory factors in sepsis-induced liver injury." (PMID 34956235, 2021). "NEAT1 is considered to work as a pivotal role in sepsis-related organ dysfunction." (PMID 34630395, 2021). "Finally, to ascertain NEAT1 promoted sepsis progression by miR-31-5p/POU2F1 axis, we co-transfected RAW264.7 cells with sh-NEAT1 (or sh-NC), sh-POU2F1, and miR-34b-5p inhibitor before LPS stimulation." (PMID 33710444, 2021). "Additionally, lncRNA NEAT1 was also elevated in the serum of patients with sepsis-induced AKI compared with controls and positively correlated with the severity of AKI." (PMID 34055659, 2021).
Sepsis (continued). "Downregulation of NEAT1 reduced apoptosis and inflammatory responses in LPS-induced sepsis." (PMID 34956235, 2021). "Nevertheless, the role of NEAT1 in sepsis-induced ALI remains elusive." (PMID 32089649, 2020). "Lately, lncRNA NEAT1 was reported to function in sepsis-induced diseases." (PMID 32414769, 2020). "Our study indicates that NEAT1 might serve as a promising target for diagnosis and therapeutics of sepsis." (PMID 32099901, 2020). "In this study, we measured the expression of NEAT1 in sepsis patients." (PMID 32099901, 2020). "Moreover, NEAT1 promoted sepsis-induced brain injury in mice by mediatingthe nuclear factor (NF)-κB pathway." (PMID 33335994, 2020). "In summary, our results demonstrated that NEAT1 could regulate sepsis progression by sponging miR-370-3p." (PMID 32414769, 2020). "Depletion of NEAT1 alleviated sepsis-induced AKI via regulating themiR-22-3p/NF-κB pathway." (PMID 33335994, 2020). "H19, SNHG16, and NEAT1 are also involved in sepsis progress." (PMID 33204219, 2020). "Collectively, these results demonstrate that silencing NEAT1 hindered the progression of sepsis." (PMID 32414769, 2020). "Compared with healthy control, sepsis group displayed abnormally elevated NEAT1 level." (PMID 32099901, 2020). "This study aimed to investigate the function andmechanism of NEAT1 in sepsis-induced AKI." (PMID 33335994, 2020). "However, little is known about the mechanism which allows NEAT1 participation in sepsis development." (PMID 32099901, 2020). "Recent finding summarized that NEAT1 could also serve as a ceRNA, which regulates sepsis-induced acute kidney injury by sponging miR-204 to target IL-6R and mediating nuclear factor kappa B (NF-κB) pathway." (PMID 32099901, 2020). "Silence of NEAT1 suppressed LPS-induced inflammatory response of macrophages by mediating miR-17-5p and TLR4, indicating that NEAT1 might be a promising target for sepsis treatment." (PMID 32099901, 2020). "In this study, the level of NEAT1 in the serum of the patients with sepsis-induced AKIwas detected." (PMID 33335994, 2020). "Measurement of NEAT1 expression in PBMCs could be considered as a good additive marker for the diagnosis of sepsis." (PMID 29463949, 2017). "We also did not conduct an in-depth study of the molecular mechanisms linking NEAT1 to sepsis." (PMID 29463949, 2017). "It is significantly upregulated in sepsis patients and contributes to disease progression by regulating inflammatory factors Lipopolysaccharide (LPS)-induced inflammation and apoptosis are mediated through the NEAT1/miR-370-3p axis, playing a central role in the initiation of sepsis." (PMID 40110044, 2025). "Moreover, exosome-derived lncRNA NEAT1 exacerbates SAE-related sepsis by promoting ferroptosis." (PMID 39768830, 2024). "However, the role of NEAT1 in sepsis-induced ferroptosis is still unclear." (PMID 35038133, 2022). "Depletion of NEAT1 could attenuate sepsis-induced AKI via regulating the miR-22-3p/NF-κB pathway." (PMID 35350698, 2022). "Levels of NEAT1 could be considered as a good predictor for the diagnosis of sepsis." (PMID 34956235, 2021). "Moreover, NEAT1 can accelerate progression of sepsis via miR-370-3p/TSP-1 axis." (PMID 34956235, 2021). "However, it is still unclear how the upregulation of NEAT1 affects LPS-induced sepsis." (PMID 33710444, 2021). "NEAT1 silencing could suppress immune responses during sepsis through miR‐125/MCEMP1 axis." (PMID 34956235, 2021). "Moreover, the levels of NEAT1 andmiR-22-3p were negatively correlated in patients with sepsis." (PMID 33335994, 2020). "In addition, the expression of miR-370-3p correlated negatively with NEAT1 in sepsis tissues." (PMID 32414769, 2020). "The NEAT1/miR-370-3p/Irak2 axis might contribute to improvements in the treatment of sepsis." (PMID 32414769, 2020).
Sepsis (continued). "All in all, our results suggest that NEAT1 might serve as a sponge, interacting with and downregulating miR-370-3p, thus altering the expression of Irak2, eventually mediating the progression of sepsis in LPS-induced RAW 264.7 and HL-1 cells." (PMID 32414769, 2020). "Hence, we hypothesized that miR-17-5p and TLR4 might be involved in NEAT1-mediated inflammation in sepsis." (PMID 32099901, 2020). "In addition, knockdown of NEAT1 alleviated LPS-triggered injury inHK-2 cells, indicating that NEAT1 might play a role in sepsis-triggered AKIprogression." (PMID 33335994, 2020). "Therefore, NEAT1 is a potentially effective marker for rapid sepsis diagnosis." (PMID 29463949, 2017). "By contrast, a positive correlation between NEAT1 and ILF3 was observed in PBMCs from patients with sepsis." (PMID 38395749, 2024). "Based on single-cell transcriptome sequencing of PBMCs from controls and septic patients, NEAT1+ CD163+, and CD16+ monocyte clusters were identified as highly correlated with clinical indicators of sepsis." (PMID 37919720, 2023). "Previous studies have also found that lncRNA HOTAIR, NEAT1, and MALAT1 were differentially expressed in sepsis patients." (PMID 34514170, 2021). "NEAT1, MALAT1, THRIL, XIST, MIAT and TUG1 are among lncRNAs that participate in the pathoetiology of sepsis-related complications." (PMID 34956235, 2021). "At present, studies of lncRNA expression in sepsis mainly focus on HOTAIR, MALAT1, NEAT1, TUG1, and UCA1." (PMID 34514170, 2021). "It was reported that NEAT1 interacts with the axis of Let-7a/TLR4 to promote inflammatory responses, thereby accelerating the progression of liver injury involved in sepsis." (PMID 34972503, 2021). "Several studies suggested the potential of other lncRNAs, such as NEAT1 and MALAT1, as biomarker for sepsis." (PMID 34055659, 2021). "Silencing of lncRNA NEAT1 can target miR‐125‐5p and regulate TRAF6/TAK1 signaling to protect against sepsis‐induced AKI." (PMID 34240756, 2021). "However, how NEAT1 mediates sepsis development is largely unknown." (PMID 32099901, 2020). "In the case of sepsis-induced AKI, NEAT1 expression correlates positively with the severity of the disease." (PMID 30717168, 2019). "qRT-PCR was used to detect differences in NEAT1 expression in PBMCs among patients with SIRS, sepsis, and healthy volunteers." (PMID 29463949, 2017). "By integrating the predictive results from five online miRNA websites, the current study proposed a potential lncRNA-miRNA-mRNA pathway: the NEAT1-hsa-miR-495-3p-ELF1 pathway, which may exert an important influence on the pathogenesis of sepsis." (PMID 40821971, 2025). "lncRNA nuclear paraspeckle assembly transcript 1 (NEAT1) modulates inflammation in several diseases, including asthma, chronic obstructive pulmonary disease (COPD), diabetic nephropathy, and sepsis." (PMID 35034548, 2022). "Furthermore, long chain genes lncRNA NEAT1 and Lnc-MALAT1 can modulate the progression of sepsis through sponging miR-370-3p [35, -37]." (PMID 35722711, 2022). "Taken together, the result revealed that miR-9-5p, sponged by NEAT1, targeted TFRC and GOT1 that overexpressed in vitro and in vivo and might promote sepsis-induced ferroptosis in brain microvascular endothelial cells." (PMID 35038133, 2022). "We found that exosomal NEAT1 transported into the cerebral cortex and functions as a ceRNA for miR-9-5p to facilitate TFRC and GOT1 expression, therefore, play important roles in sepsis-induced ferroptosis and SAE." (PMID 35038133, 2022). "Recently, emerging studies have revealed that some lncRNAs, such as NEAT1, MALAT1, and ANRIL, could participate in the progression of sepsis and serve as a potential biomarker for sepsis." (PMID 35910890, 2022).
Sepsis (continued). "Previous studies have suggested that lncRNAs may be potential biomarkers for prognosis of sepsis, such as lncRNAs MALAT1, NEAT1, RP11-1220 K2.2.1–7, ANXA3–2, TRAPPC5–1, and ZNF638–1, which have been introduced in introduction." (PMID 34483898, 2021). "In this study, our data demonstrated that NEAT1 aggravated LPS-induced inflammatory responses and cell apoptotic activity by targeting miR-31-5p and POU2F1, uncovering the potential therapeutic role of NEAT1 in sepsis-induced inflammatory response." (PMID 33710444, 2021). "Recently, the role of miR-204-5p in sepsis has been gradually explored, and it could target ANG-1 and be targeted by lncRNA NEAT1 to inhibit the damage of LPS on cells." (PMID 32484206, 2020). "Upon further analysis, NEAT1 expression levels in sepsis survivors and nonsurvivors were higher than those in the control group, but the difference between survivors and nonsurvivors was not significant (3.61 ± 0.62 versus 3.83 ± 0.57, P > 0.05)." (PMID 29463949, 2017). "We deduced that NEAT1 may be involved in the immune response in sepsis based on the close relationships between IL-6 and CXCL10 cytokines and the inflammatory response in sepsis." (PMID 29463949, 2017). "Additionally, NEAT1 also facilitates M1 polarization in macrophages through the miR-125a-5p/TRAF6/TGF-β-activated kinase 1 (TAK1) axis, underscoring its potential as a therapeutic target for sepsis." (PMID 38473915, 2024). "NEAT1 and miR-125a showed a negative correlation in sepsis patients." (PMID 36675533, 2023). "Several lncRNAs, including LINC00472, nuclear enriched abundant transcript 1 (NEAT1), colorectal neoplasia differentially expressed, and X‐inactive‐specific transcript (XIST), have been reported to participate in liver damage induced by sepsis through modulating the inflammatory response." (PMID 37829506, 2023). "For example, NEAT1 was reported to promote the inflammatory response by regulating the Let‐7a/TLR4 axis in sepsis‐induced liver injury, whereas silencing the lncRNA XIST protected against sepsis‐induced acute liver injury through the inhibition of bromodomain‐containing protein 4 expression." (PMID 37829506, 2023). "LncRNA NEAT1 increased the expression of TRAF6 and the phosphorylation of transforming growth factor-β-activated kinase 1 (TAK1) protein by binding to miR-125a-5p, eventually leading to LPS-induced macrophage polarization toward M1 and possibly ameliorating LPS-induced sepsis." (PMID 36429069, 2022). "Moreover, NEAT1 was reported to enhance the immune response through activation of the high-mobility group box 1 (HMGB1)/receptors for advanced glycation end products (RAGE) and NF-κB pathway, which exacerbated lung epithelial cell injury in sepsis mice." (PMID 34630395, 2021). "In addition, overexpressed lncRNA nuclear paraspeckle assembly transcript 1 (NEAT1) may worsen AKI via stimulating NF-κB pathway and regulating miR-204, therefore, NEAT1 may have impressive roles in sepsis-induced AKI." (PMID 31658856, 2019). "NEAT1 levels in PBMCs were significantly higher (3.76 ± 0.71-fold) in patients with sepsis than in the control group, although SIRS group NEAT1 levels are higher (1.64 ± 0.43-fold) than those of the control group, but significantly lower than those of the sepsis group (P < 0.01)." (PMID 29463949, 2017). "However, previous studies have not examined the role of NEAT1 in sepsis." (PMID 29463949, 2017). "(P < 0.01), but NEAT1 levels are significantly lower in the SIRS group than in the sepsis group, and there was no statistical significant relevance between survivors and nonsurvivors in patients with sepsis." (PMID 29463949, 2017).